SNORA58B (small nucleolar RNA, H/ACA box 58B)
Gene: Small nucleolar RNA gene on chromosome 1 (154,259,727 to 154,259,862, forward strand). Ensembl gene ENSG00000201129.
Gene Ontology:
Biological process: RNA processing
Cellular component: nucleolus
Homologues: Orthologues: chimpanzee SNORA58B (100% identical), macaque SNORA58B (98% identical), pig SNORA58B (90% identical), rabbit SNORA58B (87% identical), guinea pig SNORA58B (76% identical), mouse Gm24608 (71% identical). Paralogues in human: SNORA58 (88% identical).